RNU6-200P (RNA, U6 small nuclear 200, pseudogene)
Gene: Small nuclear RNA gene on chromosome 6 (126,590,287 to 126,590,393, reverse strand). Ensembl gene ENSG00000201613.
Homologues: Orthologues: chimpanzee U6 (99% identical), macaque U6 (88% identical), rat LOC120095818 (82% identical), rabbit U6 (79% identical), mouse Gm24878 (68% identical). Paralogues in human: RNU6-116P (89% identical), RNU6-1024P (87% identical), RNU6-1060P (87% identical), RNU6-15P (87% identical), RNU6-266P (87% identical), RNU6-672P (87% identical), RNU6-949P (87% identical), RNU6-1303P (86% identical), RNU6-211P (86% identical), RNU6-21P (86% identical), RNU6-33P (86% identical), RNU6-345P (86% identical), and 1284 more.